FABP4 (fatty acid binding protein 4)
Diseases named in the same sentence as FABP4 in open-access papers (continued):
Sharing a sentence is not in itself a finding about the gene and the disease.
acute kidney injury (13 papers, 2012 to 2025). Sudden and sustained deterioration of the kidney function characterized by decreased glomerular filtration rate, increased serum creatinine or oliguria. "Elevated renal and circulating FABP4 levels are implicated in DN pathogenesis, correlating with fibrosis, proteinuria, and acute kidney injury." (PMID 41471323, 2025). "A previous study involving ischemia–reperfusion-induced acute kidney injury (IRI-AKI) in mice found that increased expression of FABP4 initiates cellular senescence via pathways linked to oxidative stress and lipotoxicity." (PMID 41471323, 2025). "For example, Fabp4 inhibitors suppress inflammation and oxidative stress in murine and cell models of acute lung injury, and suppression of Fabp4 protects against rhabdomyolysis-induced acute kidney injury." (PMID 33506021, 2021). "This suggests that the level of plasma FABP4 increases with the progression of renal failure." (PMID 31234795, 2019). "Additionally, pharmacological inhibition of FABP4 may protect the kidneys from rhabdomyolysis-induced acute kidney injury (AKI)." (PMID 33801983, 2021). "Conversely, the downregulation of FABP4 using its specific inhibitor BMS309403 can suppress inflammation and/or apoptosis in pathological settings including acute lung injury, acute kidney injury, or diabetic nephropathy." (PMID 35955575, 2022). "Fatty acid‐binding protein 4 (FABP4) has been confirmed to be involved in the pathogenesis of ischaemia/reperfusion‐ and rhabdomyolysis‐induced acute kidney injury (AKI), and targeting inhibition of FABP4 might be a potential strategy for AKI." (PMID 31286669, 2019).
diabetic nephropathy (13 papers, 2013 to 2025). "Recent data have demonstrated that FABP4 plays a role in mediating ferroptosis, a form of cell death characterized by iron-dependent fat accumulation, which has been linked to diabetic kidney disease and retinopathy." (PMID 38731797, 2024). "Overexpressed fatty acid-binding protein 4 promotes the apoptosis of human mesangial cells (HMCs) and exacerbates diabetic nephropathy." (PMID 36339588, 2022). "For example, FABP4 mediates mesangial cell apoptosis through ER stress in diabetic nephropathy." (PMID 36452079, 2022). "FABP4 might be an early biomarker for diabetic nephropathy if combined with UACR." (PMID 29992142, 2018). "Collectively, these findings provide a robust mechanistic rationale for investigating the FABP4/FOXO1 pathway in relation to macrophage dynamics and senescence in diabetic kidney disease, supporting the relevance of our experimental model." (PMID 41471323, 2025). "The mechanisms behind the elevation of FABP4 in patients with diabetic kidney disease are not yet fully understood." (PMID 29992142, 2018).
liver fibrosis (13 papers, 2014 to 2025). "We also investigated associations between plasma proteins and improvement of liver fibrosis and found that baseline levels of FABP4 inversely correlated with the improvement in both APRI and FIB-4 observed after treatment." (PMID 32034167, 2020). "Additionally, the highly expressed genes GRIA3, FABP4, FADS2, and PRKAA2 have been implicated in lipid metabolism and liver fibrosis." (PMID 38263097, 2024). "The expression of FABP4 was found to be elevated during liver fibrosis." (PMID 36010588, 2022). "FABP4 promotes LSEC capillarization and therefore plays a crucial role during the onset and progression of liver fibrosis in mice." (PMID 36010588, 2022).
nonalcoholic steatohepatitis (13 papers, 2014 to 2025). "A recent study suggested that targeted inhibition of LPL/FABP4/CPT1 fatty acid metabolic axis can effectively prevent the progression of nonalcoholic steatohepatitis to liver cancer." (PMID 37950277, 2023). "The pharmacological inhibitors of FABP4 have been shown to be effective in treating various inflammatory diseases, including nonalcoholic steatohepatitis and vascular inflammation in both rodents and pigs." (PMID 33690220, 2021). "The FABP4 inhibitor BMS309403 treats mice with acute liver injury and non-alcoholic steatohepatitis by inhibiting proinflammatory responses in isolated rat Kupffer cells." (PMID 38341383, 2024).
Sepsis (13 papers, 2013 to 2026). Sepsis is defined as life-threatening organ dysfunction caused by a dysregulated host response to infection. "Additionally, FABP4 participates in the development of organ dysfunction caused by inflammatory responses in sepsis." (PMID 40072101, 2025). "FABP4 exacerbates inflammation and apoptosis in the kidneys during sepsis, whereas the deletion of FABP4 in RTECs showed protective effects against kidney damage." (PMID 41542228, 2026). "Future research should focus on exploring targeted intervention strategies for key pathways including TLR4, PD-L1, and FABP4, aiming to protect the structural and functional integrity of LSECs and improve sepsis-related immune imbalance and organ dysfunction." (PMID 40072101, 2025). "The roles of FABP4 and the NF-κB pathway in sepsis-related responses within LSECs require further investigation." (PMID 40072101, 2025). "The pretreatment of mice with pimozide attenuated the cecal ligation puncture-responsive induction of proinflammatory cytokines in the liver and interstitial edema in the lung in a murine sepsis model, via the inhibition of FABP-4." (PMID 37511062, 2023). "Mechanistically, TLR4 blockage improved sepsis-induced kidney injury, as well as suppressed c-Jun phosphorylation and FABP4 expression, where c-Jun knockdown also inhibited LPS-stimulated FABP4 level." (PMID 35410456, 2022). "We found that sepsis-induced FABP4 expression in RTECs was dependent on TLR4/c-Jun signaling activation, and FABP4 mediated tubular damage in septic AKI, by forming a positive feedback loop with c-Jun to amplify inflammation and apoptosis." (PMID 35410456, 2022). "Taken together, FABP4 was induced in RTECs by sepsis, while both genetic and pharmacologic inhibition of FABP4 attenuated septic AKI." (PMID 35410456, 2022). "This study aimed to assess the effects of ECGR on FABP4 and oxidative stress–related factors in a sepsis mouse model." (PMID 38559341, 2021). "The signaling pathways related to FABP4 may be key strategies to improve the pathological process of sepsis." (PMID 40072101, 2025). "Although we elucidated a critical role of tubular FABP4 in sepsis-induced kidney injury and its inhibition might be a potential strategy for treating septic AKI, there still exist several limitations to our findings." (PMID 35410456, 2022). "In the present study, we initially found that tubular FABP4 was induced by sepsis, and inhibition of FABP4 by genetic deletion or BMS309403 treatment both ameliorated impaired renal function and alleviated tubular damage through suppressing inflammation and cell apoptosis in septic AKI mice." (PMID 35410456, 2022). "Upregulation of tubular FABP4 in septic AKI is dependent on TLR4/c-Jun signaling activation, and FABP4 mediates sepsis-induced RTEC injury, likely by forming a positive feedback loop with c-Jun to aggravate inflammation and apoptosis." (PMID 35410456, 2022). "In sepsis, however, determining the increase in blood FABP4/A-FABP (fatty acid-binding protein 4) appears to be more important." (PMID 34299201, 2021). "This suggests that cogon grass root may ameliorate sepsis by increasing the platelet level, GPx3 activity, hepatocyte count, and cardiomyocyte count, as well as by reducing the lymphocyte count, monocyte count, TNF-α expression, and FABP4 level." (PMID 38559341, 2021).
lipid metabolism disorders (12 papers, 2016 to 2025). "We identified a fibroblast subset (FABP4+ fibroblasts) associated with lipid metabolism and demonstrated that lipid metabolism disorders can accelerate fibroblast formation and fibrosis." (PMID 39198543, 2024). "Inhibiting FABP4 has been shown to improve lipid metabolism disorders and reduce chronic metabolic inflammation." (PMID 40298760, 2025). "Elevated FABP4 expression is typically indicative of hepatic lipid metabolic disorders and the progression of related metabolic diseases." (PMID 41035773, 2025). "The study reveals that lipid metabolism disorders significantly contribute to cardiac fibrosis by promoting the transformation of CD34+ cells into FABP4+ fibroblasts, worsening heart fibrosis." (PMID 39198543, 2024). "FABP4 is one of the most characteristic intracellular lipid transporters in the FABPs family, which plays an important regulatory role in lipid metabolism disorders and fibrosis." (PMID 37957699, 2023). "In lipid metabolism, dual inhibitors of fatty acid-binding protein 4 (FABP4) and FABP5 significantly ameliorate lipid metabolism disorders, reduce fatty acid oxidation and utilization, and indirectly affect lactate production." (PMID 41007358, 2025).
breast tumor (11 papers, 2011 to 2025). "FABP4 is highly expressed in all subtypes of breast tumor tissue compared with normal breast tissue, and high levels of FABP4 are associated with tumor progression in BCCs." (PMID 40256431, 2025). "We also performed staining for FABP4, an adipocyte marker, and found that seven of 18 (38.8%) breast tumors stained positive and three of 20 (15%) normal breast epithelium stained positive, whereas all adipose tissue stained positive for FABP4." (PMID 21489227, 2011). "Thirdly, secreted FABP4/FAs might offer a previously underappreciated mechanism for promoting breast tumor metastasis potential." (PMID 39513934, 2024). "(E) Analysis of the staining of H&E, CD163 (brown), FABP4 (red) in primary breast tumors of patients with and without metastasis." (PMID 39513934, 2024). "(G) Analysis of FABP4 expression levels between primary breast tumors of patients with and without metastases." (PMID 39513934, 2024).
carotid atherosclerosis (11 papers, 2011 to 2023). A thickening and loss of elasticity of the walls of carotid arteries that occur with formation of atherosclerotic plaques. "In a large study the effects of low-expression variant of FABP4 were examined at population level (n = 7491) and in group of patients with advanced carotid atherosclerosis (n = 92) and myocardial infarction (n = 3432)." (PMID 25960621, 2015). "FABP4 is linked to atherogenesis, plaque instability and adverse outcome in patients with carotid atherosclerosis and acute ischemic stroke." (PMID 22174896, 2011). "FABP4 concentration is associated with carotid atherosclerosis." (PMID 28654680, 2017). "Further, a study in China has shown that there is an independent relationship between FABP-4 serum levels and carotid atherosclerosis in women." (PMID 38024104, 2023). "A correlation between FABP-4 level and the development of coronary or carotid atherosclerosis and a correlation between FABP-4 level and overweight have been reported in Asian populations." (PMID 38024104, 2023). "FABP4 was also related to atherogenesis and poor outcome in acute ischemic stroke patients with carotid atherosclerosis." (PMID 32075656, 2020). "FABP4 levels were higher in patients with carotid atherosclerosis, both systemically and within the atherosclerotic lesion, with particular high mRNA levels in carotid plaques from patients with the most recent symptoms." (PMID 22174896, 2011). "In the present study we have shown elevated FABP4 levels in patients with carotid atherosclerosis, both systemically and within the atherosclerotic lesion, with particularly high mRNA levels in carotid plaques from those with the most recent symptoms." (PMID 22174896, 2011). "To further elucidate the role of FABP4 in atherogenesis in humans, we examined the regulation of FABP4 in carotid atherosclerosis and ischemic stroke." (PMID 22174896, 2011). "We examined plasma FABP4 levels in asymptomatic (n = 28) and symptomatic (n = 31) patients with carotid atherosclerosis, as well as in 202 subjects with acute ischemic stroke." (PMID 22174896, 2011). "Increased levels of FABP4 are associated with the presence of carotid artery disease, plaque instability, and adverse outcome in patients with carotid atherosclerosis, since the highest mRNA levels of FABP4 have been observed in patients with the most recent symptoms." (PMID 34829489, 2021). "In addition, studies in humans showed that FABP4 levels are high in unstable atherosclerotic lesion of patients with carotid atherosclerosis." (PMID 24489659, 2014). "Nonetheless, our findings may suggest a link between FABP4 and atherogenesis and plaque instability in patients with carotid atherosclerosis and acute ischemic stroke." (PMID 22174896, 2011). "The current study suggests that FABP4 may be related to carotid atherosclerosis, potentially reflecting plaque instability and poor outcome." (PMID 22174896, 2011). "Furthermore, FABP4 was a determinant of carotid atherosclerosis in women but not men." (PMID 32727561, 2020).
cervical cancer (11 papers, 2018 to 2025). A primary or metastatic malignant neoplasm involving the cervix. "Specifically, in cervical cancer, upregulated FABP4 expression in cancer tissues is associated with poor OS and pelvic lymph node metastasis, indicating the prognostic value of FABP4 in cervical cancer patients." (PMID 35899119, 2022). "Then, we constructed a risk score model based on LPIN2, TEKT2, CXCL2, and FABP4, which had high accuracy in predicting the prognosis of cervical cancer patients." (PMID 34789197, 2021). "Wound healing and Transwell assays were conducted to explore the effects of FABP4 depletion on migratory and invasive abilities of cervical cancer cells." (PMID 34702269, 2021). "Edu assays showed that the proliferative abilities of cervical cancer cells (HeLa, SiHa and Caski) were decreased after knockdown of FABP4." (PMID 34702269, 2021). "In vitro, The proliferation, migration and invasion of cervical cancer cells were significantly inhibited after knocking down of FABP4, which was accompanied by elevated expression of E-cadherin and downregulated expression of N-cadherin, Vimentin and p-AKT." (PMID 34702269, 2021). "EdU assays were performed to determine whether FABP4 altered the proliferation of cervical cancer cells." (PMID 34702269, 2021). "In Cervical Cancer, FABP4 was considered to be correlated to immune cell infiltration." (PMID 32685482, 2020). "In order to investigate whether FABP4 affects the motility of cervical cancer cells, Wound healing and Transwell assays were performed and demonstrated that FABP4 knockdown led to a significant reduction in both migration and invasion in SiHa and Caski cells but not in HeLa cells." (PMID 34702269, 2021). "Subsequently, we revealed that the cytoskeletons of cervical cancer cells were reprogrammed and that the EMT process and AKT pathway were inactivated after FABP4 inhibition, which provides a new perspective on the role of EMT in LNM." (PMID 34702269, 2021). "Furthermore, loss of FABP4 suppresses the proliferation, migration and invasion of cervical cancer cells, suggesting that FABP4 has a biological function and is not merely a bystander in CCa." (PMID 34702269, 2021).
gastric cancer (11 papers, 2010 to 2025). A primary or metastatic malignant neoplasm involving the stomach. "FABP4 is highly expressed in gastric cancer tissues and is associated with tumor invasion and cachexia." (PMID 40717587, 2025). "The IVW method revealed that the interleukin 6 receptor was inversely correlated with gastric cancer progression (OR = 0.86, 95% CI = 0.74–0.99, P = .03), whereas fatty acid-binding protein 4 was found to elevate the risk (OR = 1.21, 95% CI = 1.05–1.39, P = .03)." (PMID 38306562, 2024). "FABP4 expression in gastric cancer is also associated with Helicobacter pylori infection." (PMID 36532833, 2022). "Recent studies have found that the tumor frontier region (Stroma AReactive Invasion Front Areas, SARIFA) in gastric cancer is associated with the abnormal expression of lipid metabolism-related genes (including FABP2, FABP4)." (PMID 40717587, 2025). "Our research suggests that the interleukin 6 receptor potentially mitigates, while fatty acid-binding protein 4 may contribute to the pathogenesis of gastric cancer (GC)." (PMID 38306562, 2024). "Indeed, while FABP4 deficiency resulted in increased invading cells in vitro, PPAR-γ activation with rosiglitazone blocked invasion and lung metastases, increasing the survival of mice injected intrasplenically with gastric cancer cells." (PMID 41148824, 2025). "In gastric cancer, the inhibition of PPAR-γ nuclear translocation and function by FABP4 has been described as an important mechanism regulating migration and metastasis." (PMID 41148824, 2025). "SARIFA-positivity has also been associated with the upregulation of fatty acid metabolism, including the upregulation of FABP4 and CD36 in gastric cancer." (PMID 40055484, 2025). "FABP4, a fatty acid‐binding protein, has been shown to inhibit CADM3 transcription by regulating PPAR‐γ, thereby promoting gastric cancer metastasis." (PMID 41152153, 2025).
Hyperinsulinemia (11 papers, 2017 to 2026). An increased concentration of insulin in the blood. "The inflammatory marker C-reactive protein (r = 0.29) as well as the hyperinsulinemia marker C-peptide (r = 0.28) were also correlated with FABP-4." (PMID 37833736, 2023). "The association between BMI and mortality may be partially explained by the pathway through FABP‐4, but there may be more mediator pathways (related to inflammation and hyperinsulinemia) that warrant further research." (PMID 40857027, 2026). "By contrast, a study on healthy people showed that eating a mixed meal containing propionic acid led to an increase in plasma glucagon, fatty-acid-binding protein 4, and norepinephrine concentrations, leading to glucagon-induced insulin resistance, resulting in compensatory hyperinsulinemia." (PMID 38930856, 2024).
ischemic stroke (11 papers, 2011 to 2025). A stroke disorder caused by obstruction of blood flow to the brain, due to thrombotic (local blood clot formation) or embolic (due to a blood clot or other material traveling from another site) event. "Elevated serum FABP4 levels in ischemic stroke patients correlates with early mortality and unfavorable outcomes." (PMID 41204337, 2025). "Previous study in ischemic stroke has demonstrated that FABP4 activation can upregulate MMP-9 to disrupt tight junctions and exacerbate BBB injury." (PMID 41204337, 2025). "Both 9- and 13-HODE regulate fatty acid binding protein 4 (FABP4) expression in macrophages, and both are also found at increased concentrations after ischemic stroke, possibly promoting increased inflammation for healing although PPARγ activation is often considered anti-inflammatory." (PMID 36611876, 2022). "Given its established role as a pivotal modulator of inflammatory and metabolic processes in peripheral diseases, and its recent implication in ischemic stroke outcomes, we hypothesized that FABP4 might also play a critical role in mediating microglial dysfunction and neuroinflammation after ICH." (PMID 41204337, 2025). "Furthermore, a case-control study indicated that ischemic stroke was significantly correlated with serum FABP4, which might be applied as prognostic indicator for early mortality." (PMID 30969942, 2019).